FADD (Fas associated via death domain)
Diseases named in the same sentence as FADD in open-access papers (continued):
Sharing a sentence is not in itself a finding about the gene and the disease.
lung cancer (23 papers, 2016 to 2025). A malignant neoplasm involving the lung. "A recent study demonstrated that FADD inhibition markedly suppressed lung cancer cell proliferation, while its knockdown promoted both apoptosis and pyroptosis, identifying FADD as a gene linked to PANoptosis and a potential cancer treatment target." (PMID 40649778, 2025). "For example, a recent study identified FADD, an adaptor of PANoptosis and apoptosis, as a prominent risk factor in lung cancer, mainly localized in nucleoplasm and cytosol." (PMID 38169587, 2024). "FADD serves as a key adaptor in PANoptosis and is one of the prominent risk factors for lung cancer." (PMID 38553639, 2024). "Results showed that FADD is a risk factor for lung cancer and is mainly localized in nucleoplasm and cytosol." (PMID 36874021, 2023). "Results showed that FADD is a potential risk factor for lung cancer and is mainly localized in nucleoplasm and cytosol." (PMID 36874021, 2023). "Results showed that FADD is one of the prominent risk factors in lung cancer, mainly localized in nucleoplasm and cytosol." (PMID 36874021, 2023). "Statistical univariate and multivariate regression analyses indicated that FADD is an independent factor of risk in the prognosis of a lung cancer patient (Univariate, p = 0.002, Multivariate, p = 0.02)." (PMID 36874021, 2023). "They discovered that high FADD expression in lung cancer tissues was significantly associated with the overexpression of the cyclins D1 and B1." (PMID 36348274, 2022). "Frequent FADD and caspase-10 mutations have also been reported in lung cancer, playing a role in the development of lymph node metastasis." (PMID 32847023, 2020). "In conclusion, we have provided the first evidence that the extracellular SEMA domain of 6A-FL appears to function as an attenuator of apoptosis via association of its cytosolic region with FADD in lung cancer cells." (PMID 30518871, 2018). "Activation of TLR3 by dsRNA recruits caspase 8 to form a death-signalling complex in the presence of RIP1, which appears not to be stringently dependent on Fas-associated with death domain (FADD) and results in initiation of the extrinsic apoptosis pathway in lung cancer cells." (PMID 28790362, 2017). "Further, the inhibition of FADD by in vitro experiments reduced the proliferation capacity of lung cancer cells." (PMID 36874021, 2023). "Both the DR4 and DR5 receptors are involved in the process of apoptosis in lung cancer cells through the activation of FADD." (PMID 37233477, 2023). "Based on prior surveys, the activation of TNFR1 leads to the activation of FADD, which subsequently results in apoptosis in lung cancer cells." (PMID 37233477, 2023). "Representative immunohistochemistry images obtained from the HPA database indicated a higher protein level of FADD in the lung cancer tissue." (PMID 36874021, 2023). "Inhibiting FADD reduced lung cancer cell proliferation, as assessed by CCK8 and colony formation assays." (PMID 36874021, 2023). "We next performed biological enrichment and analysis of immune infiltration to illustrate the possible effect of FADD on lung cancer." (PMID 36874021, 2023). "The results indicated that the genes FADD, TNFRSF1A, CASP9, MLKL, and CASP4 were the risk factor for lung cancer patients (p < 0.05)." (PMID 36874021, 2023). "We noticed that FADD was also highly expressed in lung cancer tissue compared to paracancerous tissue." (PMID 36874021, 2023). "Histopathology analysis of the H&E stain indicated that phosphorylated FADD mainly localized in the nucleus of lung cancer cells from a mice model." (PMID 36348274, 2022). "This meta-analysis has not demonstrated any prognostic value for phosphorylation of FADD in ser-194, contrary to other types of cancers, such as lung cancer and lymphomas, in which FADD phosphorylated in ser-194 is associated with a worse tumour prognosis." (PMID 32847023, 2020).
lung cancer (continued). "Many studies have shown that there is close link between FADD and many cancers, such as nonsmall cell lung cancer, gastric cancer and hepatocellular carcinoma (HCC)." (PMID 31443698, 2019). "In KRAS-driven lung cancer, it has been indicated that the inhibition of FADD phosphorylation suppresses tumor development, suggesting that FADD kinase is a plausible therapeutic target." (PMID 31569512, 2019). "In lung cancer, it has been demonstrated that increased levels of nuclear phosphorylated FADD induce NF-κB, which is suggested to induce the expression of cyclin D1 (CCND1) at the transcriptional level, ultimately resulting in cell cycle deregulation." (PMID 31569512, 2019). "In fact, FADD has recently been shown to promote lung cancer progression in a KRAS-driven, genetically engineered mouse model." (PMID 28212753, 2017). "In line with a requirement for caspase-8, FADD deficiency entirely abrogated TRAIL-induced cytokine secretion in human and murine lung cancer cells." (PMID 28212753, 2017). "Celecoxib was observed to induce lung cancer cell apoptosis by the intrinsic and extrinsic apoptosis pathways, including mitochondrial apoptosis pathway and FADD- and caspase-8-dependent death mechanism." (PMID 27007231, 2016). "Overexpression of FADD acted as a prognostic biomarker and cell proliferation in lung cancer." (PMID 40612112, 2025). "However, in another study, the inhibition of FADD significantly reduced the ability of lung cancer cells to proliferate, and its knockdown promoted apoptosis and pyroptosis, presenting this PANoptosis-related gene as a potential treatment target in cancer." (PMID 38169587, 2024). "In vitro experiments indicated that FADD inhibition could remarkably suppress the proliferation ability of lung cancer tissues." (PMID 36874021, 2023). "Then, we evaluated the biological role of FADD in lung cancer." (PMID 36874021, 2023). "The results from qRT-PCR depicted that the FADD was overexpressed in the lung cancer cells." (PMID 36874021, 2023). "The result of flow cytometry showed a higher apoptosis ratio of H1299 cells in sh-FADD cells compared to the control cells, indicating that the knockdown of FADD could promote apoptosis process of lung cancer cells." (PMID 36874021, 2023). "The immune-related analysis also indicated that FADD could affect many immune cells in the lung cancer microenvironment." (PMID 36874021, 2023). "After that, we looked at how FADD affected the immune microenvironment of lung cancer." (PMID 36874021, 2023). "MiR-92b-5p might promote lung cancer and non-small-cell lung cancer cell growth and controlled the G1/S cell cycle phase in human ES cells; furthermore, FADD and PER2 genes were reported to be related to reproductive deficits and embryogenesis." (PMID 31781648, 2019). "Our results indicated that FADD might also be an immune-related gene of lung cancer." (PMID 36874021, 2023). "Collectively, these findings show that FADD can act as a tumor suppressor to inhibit cellular proliferation in several cancer types, such as GBM, CRC, and lung cancer." (PMID 36348274, 2022). "In addition to residual FADD expression, the other DR-related apoptotic proteins, such as tumor necrosis factor receptor type 1-associated DEATH domain protein, might be involved in 6Acyto-induced apoptosis in lung cancer cells." (PMID 30518871, 2018). "The phosphorylation status of FADD does not seem to affect apoptosis and has also been related with poor prognosis in lymphomas and lung cancer via NF-kB-cyclin D1 activation; nevertheless, its impact on HNSCC is controversial." (PMID 32847023, 2020). "Also in lung cancer, the induction of mitosis seems to depend on activation of KRAS and CK1α phosphorylation of FADD during G2–M, where FADD interacted with G2–M cell-cycle regulatory components PLK1, AURKA, and BUB1." (PMID 31569512, 2019).
lung cancer (continued). "Notably, we found that juglanin could induce both intrinsic and extrinsic pathways to enhance apoptotic response in lung cancer cells, proved by the elevated Bad/Bax/Caspase-9 and TRAIL/FADD/Caspase-8, respectively." (PMID 29212196, 2017).
leukemia (17 papers, 2010 to 2025). A malignant (clonal) hematologic disorder, involving hematopoietic stem cells and characterized by the presence of primitive or atypical myeloid or lymphoid cells in the bone marrow and the blood. "Based on the database of GWAS catalog and GTEx Portal, 17 SNPs associated with leukemia susceptibility were found to be linked to FADD expression." (PMID 35637951, 2022). "We performed a bioinformatic analysis in an attempt to discover SNP loci associated with both leukemia susceptibility and FADD expression using the database of GWAS catalog and GTEx Portal." (PMID 35637951, 2022). "The pro-apoptotic effects of EFW on human leukemia cells are exerted by inducing a loss of the mitochondrial membrane potential, the release of cytochrome C, and increasing levels of FADD and Fas/TNFRSF6 proteins." (PMID 23377135, 2013). "Smac mimetic BV6 enhanced TNF-induced cell death in leukemia cells in 2 different ways: necroptosis, when the cells were apoptosis resistant (FADD– and caspase-8–deficient), and caspase-8–dependent apoptosis in apoptosis-proficient cells." (PMID 22929310, 2012). "Notably, leukemia cells with a reduced expression of death receptor genes (Fas associated via death domain (FADD), BH3 interacting domain death agonist (BID), caspase 8 (CASP8), TNF receptor superfamily member 10b (TNFRSF10B)) have been associated with patients showing no response." (PMID 38397092, 2024). "Taken together, we show the key role of FADD and caspases in a leukemia cells response to treatment with various anti-cancer drugs." (PMID 33800107, 2021). "Khwaja and colleagues reported that inhibition of the FADD/caspase signaling pathway sensitizes leukemia cells to TNFα-induced cell death." (PMID 32194778, 2020). "Taken together, these results provide insight into the mechanism of apoptosis induction by PCI-24781 in leukemia by highlighting the roles of caspase-8, FADD and increased superoxide levels." (PMID 20145726, 2010). "FADD downregulation is more frequent in leukemia and lymphoma than in any other cancer type." (PMID 36499482, 2022). "The knockdown of FADD or FADD−/− leukemia Jurkat T-cells failed to induce NF-κB signaling upon TRAIL stimulation." (PMID 38542202, 2024). "Autophagic cell death is also induced by many other stimuli, such as platonin-treated leukemia cells, TNFα-treated cells, and death receptor-mediated cell death in cells lacking FADD, caspase activation, or NF-κB activation." (PMID 24947784, 2014).
glioma (16 papers, 2006 to 2025). A benign or malignant brain and spinal cord tumor that arises from glial cells (astrocytes, oligodendrocytes, ependymal cells). "Of the seven prognostic necroptosis genes, RIPK1, RIPK3, FAS, and FADD were used to construct the risk signature that accurately predicts the prognosis of glioma patients." (PMID 35719998, 2022). "Previous studies have demonstrated that adenovirus or retrovirus-mediated transfer of the FADD gene induces apoptosis in glioma cells." (PMID 38542202, 2024). "Studies propose that EZH2 can enhance glioma resistance to temozolomide (TMZ) by regulating the FADD/PARP1 axis." (PMID 39069522, 2024). "Previous studies have reported increased TLR2 expression in advanced ovarian cancer patients, and abnormal FADD expression has been noted in various solid tumors, including glioma, non-small cell lung cancer (NSCLC), and hepatocellular carcinoma (HCC)." (PMID 39669578, 2024). "Previous approaches have successfully delivered a fusion of the FADD gene with the human telomerase reverse transcriptase (hTERT) promoter, resulting in significant apoptosis induction in glioma cells." (PMID 38542202, 2024). "Taken together, these findings demonstrate that JNK1 induces G2/M cell cycle arrest and apoptosis in PCa cells by activating FADD, whereas ERK facilitates the apoptosis of glioma cells by upregulating FADD levels." (PMID 36348274, 2022). "They performed immunofluorescence assay using glioma cell model and discovered that FADD overexpression increased temozolomide (TMZ)-induced DNA damage in glioma cells, whereas FADD knockdown decreased TMZ-induced DNA damage in ATRX knockout glioma cells." (PMID 36348274, 2022). "They discovered that the levels of phosphorylated ERK was significantly upregulated in U87MG and T98G cells treated with miltefosine, and activated ERK increased FADD expression, resulting in enhancement of glioma cell apoptosis induced by miltefosine." (PMID 36348274, 2022). "The aberrant expression of FADD has been observed in multiple solid tumors, such as glioma, non-small cell lung cancer (NSCLC), and hepatocellular carcinoma (HCC)." (PMID 36348274, 2022). "In summary, we have demonstrated the therapeutic efficacies of pG8-FasL/FADD amplicon viruses in human glioma cells derived from established cell lines and patients biopsy samples." (PMID 20942909, 2010). "Furthermore, the data from WB, qRT-PCR, and immunofluorescence assays revealed that FADD expression was inhibited in TMZ-resistant glioma cells by ATRX by promoting the trimethylation of histone H3K27 in the FADD promoter region." (PMID 36348274, 2022). "The risk scores of glioma patients were calculated based on the coefficient and expression levels of each gene and the formula was as follows: risk score = 0.431 * RIPK1 +0.227 * RIPK3 + 0.302 * FAS +0.373 *FADD." (PMID 35719998, 2022). "FADD can inhibit drug resistance in glioma cells through enhancing DNA damage induced by TMZ." (PMID 36348274, 2022). "Recently, inducible FADD was also shown to induce apoptosis in resistant glioma cells." (PMID 20942909, 2010). "Since the Fas/FasL receptor pathway converges at FADD, we hypothesized that the overexpression of FADD could sensitize glioma cells to FasL-induced apoptosis." (PMID 20942909, 2010). "The high expression of TLR3 in lower grade glioma (LGG) and LUSC; FASLG in LGG, UVM, KIRC, and THYM; RIPK3 in LGG, KIRC, and LUSC; RIPK1 in LGG and THCA; FAS in LGG, UVM, and THYM; MLKL in LGG, UVM, and LUAD; FADD in LGG and HNSC; and TNF in UVM and CESC was associated with poor survival." (PMID 35748782, 2022). "More importantly, we showed that the co-expression of FasL and FADD could elicit potent anti-tumor effect, which was enhanced in the presence of temozolomide, resulting in prolonged survival of mice bearing orthotopic gliomas." (PMID 20942909, 2010). "A number of solid malignancies, such as gliomas, NSCLC, and hepatocellular carcinoma (HCC), have been shown to express FADD aberrantly." (PMID 40141789, 2025).
glioma (continued). "In hepatoma cells, primary glioma and esophageal squamous cell carcinoma cells DISC analysis revealed that bortezomib enhanced the recruitment of TRAIL-receptors, FADD and caspase-8 upon rhTRAIL stimulation." (PMID 41180258, 2025). "As shown by the bean plot, 7 genes (RIPK1, RIPK3, FAS, FADD, FASLG, TLR3, and TNF) were upregulated in the glioma tissues with p <0.001." (PMID 35719998, 2022). "Taken together, these results indicate that the suppression of FADD is responsible for ATRX mediated PARP1 stabilization and TMZ resistance in glioma cells." (PMID 32194873, 2020). "Given that gliomas are heterogeneous in nature, the combination of TMZ and our cell cycle-regulated FasL and FADD vector should confer added survival benefits." (PMID 20942909, 2010). "LM-G-4, a TRAIL resistant line, expressed higher levels of DR5, caspase-8 and FADD than D2247, arguing that factors other than the levels of these proteins influence TRAIL sensitivity in glioma cells." (PMID 18594532, 2008). "Our results indicated that ATRX was upregulated via DNA demethylation mediated by STAT5b/TET2 complex in TMZ resistant glioma cells and that ATRX promoted PARP1 stabilization through down-regulating FADD by suppressing of H3K27me3 enrichment in FADD promoter region." (PMID 32194873, 2020). "Knockdown of FADD expression decreased TMZ induced PARP1 cleavage, activation of CASP8 and CASP3, and degradation of BCL2 and BCL-XL in ATRX knockout cells, indicating that suppression of FADD is responsible for ATRX mediated PARP1 stabilization and TMZ resistance in glioma cells." (PMID 32194873, 2020). "Aside from the possible role in immune surveillance, some of the glioma cells are resistant to Fas-induced apoptosis, possibly due to low levels of Fas expression, or absence of FADD or caspase 8 expression." (PMID 20942909, 2010). "Therefore, we speculated that an even greater therapeutic efficacy of pG8-FasL/FADD and TMZ could be achieved in human glioma cells with generally low MGMT activity." (PMID 20942909, 2010).
hepatocellular carcinoma (14 papers, 2011 to 2025). A malignant tumor that arises from hepatocytes. "For instance, in hepatocellular carcinoma, FADD-driven inflammation suppresses the NF-κB pathway, triggering compensatory proliferation and contributing to malignant progression." (PMID 40740228, 2025). "Chen Tian-ke’s team confirmed that AFP promoted the proliferation of hepatocellular carcinoma by inhibiting the HUR-mediated Fas/FADD apoptosis signaling pathway." (PMID 37312022, 2023). "AFP (Alpha Fetoprotein) encodes alpha fetoprotein, which is commonly associated with hepatocellular carcinoma in adults, and AFP can promote hepatocellular carcinoma progression by inhibiting the HuR-mediated Fas/FADD apoptotic pathway." (PMID 37919386, 2023).